SET (SET nuclear proto-oncogene)
Diseases named in the same sentence as SET in open-access papers (continued):
Sharing a sentence is not in itself a finding about the gene and the disease.
tumor (continued). "We then determined SET expression in clinical samples using immunohistochemistry analysis in 163 NSCLC specimens and 42 adjacent normal tissues and found that SET was overexpressed in 91.4% of tumor samples (149 of 163)." (PMID 25945834, 2015). "Furthermore, SET antagonist FTY720 treatment increased PP2A activity, impaired cell proliferation, clonogenic potential and tumor growth of NSCLC cells in vitro and in vivo." (PMID 25945834, 2015). "Furthermore, we observed that restoration of PP2A using SET antagonist FTY720 impaired proliferative and invasive potential in vitro, as well as inhibited tumor growth in vivo of NSCLC cells." (PMID 25945834, 2015). "Since exogenous and endogenous sphingosine bind wt-I2PP2A/SET, but not K209D-I2PP2A/SET, in A549 cells, we examined whether sphingosine analogue FTY720, which was shown to inhibit tumour growth, binds/targets I2PP2A/SET." (PMID 23180565, 2013). "Targeting I2PP2A/SET exogenously with a sphingolipid analogue drug that mimics ceramide and/or sphingosine could potentially bind I2PP2A/SET and reactivate PP2A tumour suppressor signalling." (PMID 23180565, 2013). "Therefore, we hypothesized that SET knockout may affect the activation of ERK and P38 signaling in macrophages and regulate macrophage chemotaxis toward hypoxic tumor supernatants." (PMID 36224346, 2022). "However, FTY720 treatment had no additional effect on serum LDH in tumours expressing shRNA against I2PP2A/SET, consistent with the lack of enhanced tumour growth inhibition by FTY720." (PMID 23180565, 2013). "The expression of SET, PP2A and β-catenin at the mRNA level was tested in non-malignant and malignant tissues, and SET was found to be markedly elevated in 70.9% of the tumor samples (22 out of 31 samples)." (PMID 24944693, 2014). "Knockdown of I2PP2A/SET alone inhibited tumour growth ∼85%, however, FTY720 had no additional effects on tumour suppression in response to I2PP2A/SET knockdown." (PMID 23180565, 2013). "Interestingly, the structural details of specific interactions between SET and the PP2A holoenzyme with specific A, B, and C subunits with tumor suppressor functions have not yet been described." (PMID 25642418, 2014). "Our novel data suggested that FTY720, but not P-FTY720, directly binds and targets I2PP2A/SET, mimicking ceramide/sphingosine, which activates tumour suppressor PP2A, subsequently suppressing lung tumour growth selectively via inducing RIPK1-mediated necroptosis." (PMID 23180565, 2013). "In addition, depletion of SET and/or ZBTB11 did not impair primary tumor growth." (PMID 38355937, 2024).
hematological malignancies (5 papers, 2015 to 2023). "We reviewed the characteristics and prognostic significance of the SET-CAN/NUP214 fusion gene in hematological malignancies." (PMID 35905214, 2022). "The mechanism, clinical characteristics, therapy and prognosis of the SET-CAN/NUP214 fusion gene in hematological malignancies require further research." (PMID 35905214, 2022). "SET-CAN/NUP214 fusion gene encodes a protein containing an almost complete portion of SET fused to the carboxy-terminal two-thirds of CAN, which is a rare gene rearrangement occurs primarily in hematological malignancies." (PMID 37909026, 2023). "In pediatric hematological malignancies, a recurrent chromosomal translocation forms a NUP98-NSD1 fusion with SET-dependent leukemogenic activity, which seems targetable by small molecule inhibitors." (PMID 34575025, 2021). "SET (or I2PP2A) is a potent endogenous inhibitor of the tumor-suppressor PP2A as PP2A acts as a negative regulator of several survival and proliferation pathways that are aberrantly activated in hematological malignancies." (PMID 25763353, 2015).
infection (4 papers, 2009 to 2020). The state of being infected such as from the introduction of a foreign agent such as serum, vaccine, antigenic substance or organism. "Because NM23-H1 knockdown interfered with HIV-1, we reasoned that the larger SET complex facilitated infection." (PMID 19266025, 2009). "The ISD bait method was validated by identifying known dsDNA sensors including HMGB1, HMGB2, and HMGB3, components of the AIM2 inflammasome, and the SET complex that plays a role in HIV-1 retroviral detection and infection." (PMID 33042865, 2020). "Furthermore, we describe the development of a novel imaging system that uses Template Activating Factor-I (TAF-I/SET), a cellular chromatin protein tightly bound to protein VII upon infection." (PMID 26332038, 2015).
neurodegenerative disease (3 papers, 2018 to 2022). A disorder of the central nervous system characterized by gradual and progressive loss of neural tissue and neurologic function. "Additionally, there are other endogenous regulators, that include SET and PTPA, which may contribute to PP2A inhibition in neurodegenerative diseases." (PMID 29950985, 2018).
blood tumor (2 papers, 2017 to 2023). "SET is overexpressed in different solid and hematological tumors; however, the causes of this overexpression are still unknown." (PMID 28903318, 2017). "Nevertheless, despite the importance of SET, and the prognostic impact of SET overexpression in both solid and hematologic tumors, little is known about the mechanisms involved in the transcriptional regulation of this oncogene." (PMID 28903318, 2017). "Our group and others have demonstrated that overexpression of SET, a potent PP2A endogenous inhibitor, is a recurrent event that causes PP2A inactivation in hematological neoplasms." (PMID 28903318, 2017).
SET also shares sentences with these, for which no sentence is quoted: hepatocellular carcinoma (4 papers); multiple myeloma (4); neuroblastoma (3); T-cell acute lymphoblastic leukemia (3); Wilms tumor (2); B-cell acute lymphoblastic leukemia (1); B-cell non-Hodgkin lymphoma (1); bladder cancer (1); bone cancer (1); breast tumor (1); Cerebral ischemia (1); chordoma (1); Coffin-Siris syndrome (1); colon adenocarcinoma (1); developmental delay (1); esophageal squamous cell carcinoma (1); Ewing sarcoma (1); hepatoblastoma (1); hypospadias (1); invasive ductal carcinoma (1); liver cancer (1); mental illness (1); mental retardation, autosomal dominant 58 (1); metastatic melanoma (1); microencephaly (1); myeloid sarcoma (1); myeloproliferative neoplasm (1); neurological disease (1); osteoporosis (1); ovarian tumor (1).
A further 4 diseases each share a sentence with SET in 1 paper.